GRB2 (growth factor receptor bound protein 2)
Diseases named in the same sentence as GRB2 in open-access papers (continued):
Sharing a sentence is not in itself a finding about the gene and the disease.
cervical carcinoma (7 papers, 2017 to 2025). A carcinoma arising from either the exocervical squamous epithelium or the endocervical glandular epithelium. "Notably, GRB2 protein overexpression has been documented in various malignancies, including cervical cancer, and is strongly associated with enhanced cancer cell motility, migration, and invasiveness." (PMID 40733070, 2025). "MALAT1 could modulate GRB2 expression via competing miR-124 to promote high-risk human papillomavirus (HR-HPV)-positive cervical cancer cell growth and invasion." (PMID 28439401, 2017). "In conclusion, DDR1 binds directly to GRB2 and then affects downstream phosphorylation signals, ultimately exacerbating the metastasis of cervical cancer cells." (PMID 39567474, 2024). "In HPV 16 positive cervical cancer, Growth factor receptor-bound protein 2 (GRB2), responsible for cell communication, is highly expressed." (PMID 36144454, 2022). "In addition, the reduced migration rate and invasive cell number, and attenuated phosphorylation of 4EBP1 and EPHA2 supported that DDR1 influenced the migration and invasion of cervical cancer via GRB2." (PMID 39567474, 2024). "Furthermore, DDR1 bound directly with Src homology 2 domain of growth factor receptor bound protein 2 (GRB2) which mediated the function of DDR1 in the malignant behaviors of cervical cancer and the phosphorylation of downstream targets." (PMID 39567474, 2024). "Mechanistically, whether SOX2 had a regulatory effect on DDR1 transcription and whether GRB2 mediated DDR1 function in cervical cancer were explored." (PMID 39567474, 2024). "We next asked whether DDR1 played a role through GRB2 in cervical cancer." (PMID 39567474, 2024). "However, whether GRB2 serves as an adaptor protein mediating the role of DDR1 in cervical cancer remains unknown." (PMID 39567474, 2024). "The molecular docking analysis of the 306 differential proteins with known cervical cancer–related targets identified intersecting proteins within the PI3K/AKT signaling pathway: PIK3R2, GRB2, MAPK1, FGF2, and PRKCA." (PMID 40733070, 2025). "In summary, the present study suggests that DDR1 bound to the SH2 domain of GRB2, thereby affecting downstream phosphorylation signals and ultimately exacerbating the migration, invasion and EMT of cervical cancer cells." (PMID 39567474, 2024). "The protein–protein interaction study indicates the interacting partners of EREG, and they were EGF, TGFA, GRB2, and HRAS, and most of them regulate cervical cancer." (PMID 34439555, 2021). "In Figure, two TIR fluorescence images are depicted for HeLa cervix carcinoma cells stably transfected with Grb2-YFP, and transiently transfected with EGFR-CFP without further stimulation." (PMID 30717378, 2019).
schizophrenia (7 papers, 2010 to 2023). A major psychotic disorder characterized by abnormalities in the perception or expression of reality. "We identified GRB2 as a candidate gene for schizophrenia in our previous study through a network-assisted strategy and then validated it in the Irish Case Control Study of Schizophrenia (ICCSS) sample." (PMID 22792057, 2012). "Here, using an independent strategy and datasets, we again identified this gene, further supporting GRB2 as a candidate gene for schizophrenia." (PMID 22792057, 2012). "Using the Haploview program, we tested the association of seven tagSNPs in gene GRB2 and two tagSNPs in gene HSPA5 in our Irish Case-Control Study of Schizophrenia (ICCSS) sample (1,021 cases and 626 controls)." (PMID 20613869, 2010). "There have been a few studies which suggested the association between GRB2/GRAP2 and schizophrenia, but we suspect GRAP2 might be actively involved in integrating and transmitting the effects of gene deletion leading to the expression of neuropsychiatric diseases." (PMID 37872602, 2023).
colon cancer (6 papers, 2014 to 2025). "For example, NSUN2 is involved in GRB2-mediated colon cancer cell migration." (PMID 40279954, 2025). "We entered the analyzed colon cancer marker gene set (CD2AP, GRB2, WASL, SRC, CTTN, CAPZA1, and Tks4) into this tool to elucidate which cancer hallmark-related pathways are influenced by these proteins." (PMID 39234565, 2024). "The expression levels of CD2AP, GRB2, WASL, and CAPZA1 are generally downregulated, while those of SRC and CTTN are upregulated in colon cancer samples compared with their levels in normal samples at the RNA and/or protein levels." (PMID 39234565, 2024). "This analysis revealed that the expression levels of WASL, GRB2, SRC, and Tks4 were the most important variables among the entire gene set; therefore, we conclude that the examination of these four genes should be sufficient for colon cancer diagnosis." (PMID 39234565, 2024). "Apart from acting on the PI3K pathway through GRB2, whether PRR14 has another mechanism through which it regulates the development and progression of colon cancer, remains to be determined." (PMID 31596887, 2019).
glioblastoma (6 papers, 2018 to 2025). The most malignant astrocytic tumor (WHO grade IV). "On the other hand, GRB2 is a key protein in epidermal growth factor receptor signaling in the Glioblastoma tumoroginesis pathway." (PMID 30059495, 2018). "In glioblastoma cells, NK1R-mediated EGFR transactivation was involved with a PTX-sensitive Gα protein; activated EGFR complex was found to contain adaptor proteins SHC and Grb2." (PMID 35013118, 2022).
liver cancer (6 papers, 2018 to 2023). An epithelial or non-epithelial malignant neoplasm that arises from the liver. "However, it also remains unclear whether the anticarcinogenic activities of genistein are associated with Grb2 during the development of chronic HBV infection into liver cancer." (PMID 32298608, 2020). "Our data also pave the way for further research on Grb2 during the development of chronic HBV infection in liver cancer." (PMID 32298608, 2020). "Hence, the mechanisms of genistein and Grb2 expression in HBV-related liver cancer should be further studied." (PMID 32298608, 2020). "Furthermore, DHA also inhibits GRB2 and GSK3β, genes which are downstream in the ERBB signaling pathway found in our liver cancer meta‐analysis and known to promote multiple types of cancers." (PMID 37859621, 2023).
acute myeloid leukemia (5 papers, 2020 to 2022). Acute myeloid leukemia (AML) is a group of neoplasms arising from precursor cells committed to the myeloid cell-line differentiation. "The ASO BP1001 targeting the translation initiation site of the growth factor receptor-bound protein 2 (Grb2) has been tested in acute myeloid leukemia (AML) and high-risk myelodysplastic syndromes (MDS) and showed a good safety profile and evidence of antileukemic activity in a phase I study." (PMID 32375354, 2020). "It is worth to mention that a few genes with a role in acute myeloid leukemia: GRB2, CSFIR, MARCKS and PDGFB were upregulated; FLT1, IL6, PIK3C2B, BALAP3 and MAPK10 were downregulated." (PMID 36413544, 2022). "For example, the three genes GRB2, FLT3, and PML, which were found in the acute myeloid leukemia (AML) signaling network, were considered key drug target genes." (PMID 34238960, 2021).
diabetes (5 papers, 2019 to 2024). "protein kinase CAMP-dependent type II regulatory subunit α, growth factor receptor bound protein 2, and guanine nucleotide-binding protein G(s) in the urine of diabetic patients were downregulated, which was associated with diabetes." (PMID 36749274, 2023). "Another research focusing on advanced glycation product receptors (AGERs) relating to diabetes and aging mentioned that tyrosine phosphorylation has been shown to cause MAPK activation through Grb2 and Sos." (PMID 30669571, 2019). "Spearman correlation analysis showed that GRB2 concentrations were negatively correlated with HDL-C, and positively associated with duration of diabetes, waist-to-hip ratio (WHR), TC, HBA1c, FPG, FINS, homeostasis model assessment-insulin resistance index (HOMA-IR), Hs-CRP, IL-6 and CIMT (P<0.01)." (PMID 36176460, 2022). "Furthermore, serum GRB2 levels (P<0.001) remained independently related to CIMT after adjusting for the age, sex, duration of diabetes, and Body Mass Index (BMI) variables." (PMID 36176460, 2022). "This was the first study to investigate blood GRB2 levels in type 2 diabetes mellitus(T2DM) patients with carotid atherosclerosis (CAS), exploring its relationship with various metabolic indicators, and further, examining whether GRB2 has an AS effect in patients with T2DM." (PMID 36176460, 2022).
glioma (5 papers, 2017 to 2025). A benign or malignant brain and spinal cord tumor that arises from glial cells (astrocytes, oligodendrocytes, ependymal cells). "It was reported that MAP2 interacts with Grb2 in glioma cells and that downregulation of MAP2 promotes the interaction between Grb2 and SOS." (PMID 39002671, 2024). "It was suggested that MAP2 downregulation via miR-484 enhances Grb2–SOS interaction and subsequently upregulates ERK signaling pathway which leads to enhanced stemness of glioma cells." (PMID 39002671, 2024). "We randomly selected four additional genes (AKT2, AKT3 GRB2 and MMP2) from the “glioma” pathway, other than the validated targets of the key miRNAs.to check for downstream effect of miRNA overexpression." (PMID 29769662, 2018).
ischemic stroke (5 papers, 2016 to 2025). A stroke disorder caused by obstruction of blood flow to the brain, due to thrombotic (local blood clot formation) or embolic (due to a blood clot or other material traveling from another site) event. "GRB2 plays a key role in neuroprotection, reducing neuronal damage through the regulation of autophagy and the Akt/mTOR pathway in ischemic stroke." (PMID 40299522, 2025). "Higher levels of MEG3 in ischemic stroke lead to the upregulation of GRB2 by binding to and inhibiting miR-378, resulting in the destruction of the Akt/mTOR pathway." (PMID 39021183, 2024). "For instance, the lncRNA MEG3 inhibits neuronal death and neurological problems in mice with ischemic stroke through the MEG3/miR-378/Grb2 axis and inhibits neuronal autophagy and neurodegeneration by silencing Grb2." (PMID 36671403, 2022). "Taken together, the data suggest that Abca13 and Grb2 may be more important in ischemic stroke after hUC-MSC transplantation." (PMID 27699085, 2016).
bladder cancer (4 papers, 2013 to 2024). "In bladder cancer, the Grb2 and SOS expression levels are higher compared to those in a normal bladder." (PMID 39272802, 2024). "BPV E5 induces recruitment of GRB2 to activated PDGFβR (pPDGFβR), contributing to cell transformation in vitro; furthermore, pPDGFβR recruits GRB2-Sos1 which promote Ras activation in bovine urinary bladder cancer, suggesting a role of this pathway in BPV-induced carcinogenesis." (PMID 23936786, 2013). "GRB2 is known to be a key molecule in intracellular signal transduction through the EGF receptor (EGFR), and can be overexpressed in tumors of breast and bladder cancers." (PMID 23922722, 2013). "Therefore, the amplification of the Grb2 and SOS proteins may be crucial in the tumorigenesis of bladder cancer as well." (PMID 39272802, 2024).
breast tumor (4 papers, 2013 to 2024). "The role of GRB2 in tumour progression has been studied widely in breast tumour, as GRB2 has been found to be highly expressed in many types of cancers, especially breast tumours." (PMID 30087284, 2018). "Consistent with the finding that phosphorylation of SHP-2 on Y279 down-regulates growth factor-induced sustained ERK activation and proliferation through Abl kinase, we found GRB2-SHP2pY279 downregulated in breast tumor cells." (PMID 23826330, 2013). "GRB2 has previously been reported to localise in the nucleus in breast tumours." (PMID 30087284, 2018). "Parallel to this, we observed upregulated GRB2- SPTAN1pY2430 interaction in breast tumor cells." (PMID 23826330, 2013). "In breast tumor tissue, 58% of GRB2 protein is in the nucleus, while in normal breast tissue, 22% of GRB2 is present in the nucleus." (PMID 38540680, 2024). "GRB2 interaction with LAT and LAX1 observed in breast tumor cells may be an indirect interaction through PLCG1, VAV or PIK3R1." (PMID 23826330, 2013).
esophageal cancer (4 papers, 2010 to 2023). A primary or metastatic malignant neoplasm involving the esophagus. "As reported, the m5C writer NSUN2 was proven to stabilize the GRB2 mRNA via m5C dependent manner in esophageal cancer." (PMID 35603206, 2022). "Thus to support the antagonistic activity of p66shc towards growth factor induced MAPK activation, we studied the expression of Grb2 and Ras proteins in esophageal cancers." (PMID 20565814, 2010). "We observed equal expression of Grb2 in esophageal cancers with respect to adjacent normal." (PMID 20565814, 2010).
lung adenocarcinoma (4 papers, 2015 to 2022). A carcinoma that arises from the lung and is characterized by the presence of malignant glandular epithelial cells. "It was thus inferred that JUN, NR3C1, and GRB2 were most likely to be new candidate lung adenocarcinoma-related genes." (PMID 26402252, 2015). "GRB2 was evaluated as a prognostic marker for lung adenocarcinoma." (PMID 33488678, 2020).
type 2 diabetes (4 papers, 2013 to 2023). "Another interesting genome-wide significant signal linked to sight-threatening retinopathy has been identified in the vicinity of the GRB2 gene (encoding growth factor receptor bound protein 2) in a meta-analysis combining White and Asian populations with type 1 and type 2 diabetes." (PMID 37452207, 2023).
Alzheimer disease (3 papers, 2017 to 2023). A progressive, neurodegenerative disease characterized by loss of function and death of nerve cells in several areas of the brain leading to loss of cognitive function such as memory and language. "GRB2 promotes autophagic removal of amyloid-β precursor overload and reduces Alzheimer’s disease-like pathology in neuronal cells." (PMID 28792504, 2017).
asthma (3 papers, 2021 to 2023). "Several groups have shown the association between GRB2 and asthma; however, we are the first to link increased GRB2 expression to CC16 deficiency, which may have an impact on asthma development, especially in those individuals prone to persistent Mp infections." (PMID 37566063, 2023). "Further evaluations showed that the GRB2 gene in both COPD and MLD and the ESR1 and IRF7 genes in asthma and IPF had the highest association with the other genes, respectively." (PMID 37422662, 2023). "Using these datasets, we identified that GRB2 had variants that were significantly associated (p < 0.05) with a decline in forced expiratory volume in one second (FEV1; lung function) and/or an increased risk of asthma development." (PMID 37566063, 2023).
chronic myeloid leukemia (3 papers, 2012 to 2024). "Moreover, bosutinib, a tyrosine kinase inhibitor, is perhaps the best candidate identified, as it is already in use against chronic myeloid leukemia and was found to target five upregulated proteins (CDC37, CDKN1B, GRB2, RASSF1, and SMAD2)." (PMID 39202022, 2024).
cytomegalovirus infection (3 papers, 2015 to 2025). A herpesvirus infection caused by Cytomegalovirus. "It is also worth mentioning that HCMV infection enhances the expression of Grb2 and DDX3X, facilitating viral replication and spread." (PMID 40592844, 2025).
diabetic retinopathy (3 papers, 2017 to 2022). "Previous studies have identified several candidate genes associated with the progression of diabetic retinopathy; examples of such candidate genes that were selected in our studies and found to be associated with diabetic retinopathy are GRB2, GHRHR, BMP2, and GAPDH." (PMID 36360284, 2022). "In diabetic retinopathy 34 genes including AP15, GRB2, IL17A, PLXDC1, C5 and L1CAM were studied in a single year in which, C5 and L1CAM are reported as recently as in 2016." (PMID 28761062, 2017).
lymphoma (3 papers, 2008 to 2021). A malignant (clonal) proliferation of B- lymphocytes or T- lymphocytes which involves the lymph nodes, bone marrow and/or extranodal sites. "In fact, the relationship between IL-6 upregulation and Grb2 activation has been reported in human myeloma and lymphoma." (PMID 33829014, 2021). "Finally, GRB2 may differentially regulate cytokine production in T cell lines derived from lymphomas, such as HuT78 T cells, compared to primary T cells." (PMID 25870599, 2015). "As mentioned in the introduction, BCR-ABL with a mutation at the tyrosine-177 residue – a high affinity-binding site for the Grb2 SH2 domain – induced a T cell leukemia and lymphoma after a prolonged latent period." (PMID 18577264, 2008). "In this model system, BCR-ABL with a mutation (Y177F) at the tyrosine-177 residue – a high affinity-binding site for the Grb2 SH2 domain when phosphorylated – induced a T cell leukemia and lymphoma after a prolonged latent period." (PMID 18577264, 2008).
neuroblastoma (3 papers, 2017 to 2024). Neuroblastoma (NB) is the most common solid, extracranial childhood tumor. "In this system, simultaneous transfection of AICD followed by Aβ treatment in human neuroblastoma cells showed significant upregulation of Grb2 at both protein and transcript levels." (PMID 28360125, 2017).
renal cell carcinoma (3 papers, 2015 to 2022). "In contrast, upregulated Grb2 is also a predictive biomarker for the progression of renal cell cancer due to its growth-promoting effects." (PMID 33829014, 2021).
Sepsis (3 papers, 2014 to 2023). Sepsis is defined as life-threatening organ dysfunction caused by a dysregulated host response to infection. "VPS9D1 has also been shown to interact with GRB2 (growth factor receptor-bound factor 2), which was also more highly expressed in sepsis survivors and in those with VPS9D1 variants." (PMID 25538794, 2014). "The genes co-regulated by Acu-exo and sepsis were derived from multiple organs and systems, their interacting genes(HSP90AA1, GRB2, EGFR etc.)and signaling pathways(MAPK, TNF, JAK-STAT etc.)were involved in inflammation, immune regulation, metabolism, and cell proliferation and apoptosis." (PMID 37635258, 2023).
Stroke (3 papers, 2016 to 2024). Sudden impairment of blood flow to a part of the brain due to occlusion or rupture of an artery to the brain. "GRB2 has been implicated in neuronal autophagy in stroke neuropathology via the suppression of the Akt/mTOR pathway." (PMID 35250546, 2022). "Grb2, Acot11, Acat2, Scp2, Anp32b and Ppp2r5d were down-regulated after stroke." (PMID 27699085, 2016).
autoimmune disease (2 papers, 2021 to 2024). A disorder resulting from loss of function or tissue destruction of an organ or multiple organs, arising from humoral or cellular immune responses of the individual to their own tissue constituents. "This is worth considering particularly because several autoinflammatory and autoimmune diseases have been attributed to GRB2-linked molecular assemblies." (PMID 38433833, 2024). "Besides, GRB2 makes a great difference in the progression of autoimmune diseases due to its involvement in T cells’ development." (PMID 33535181, 2021).
Burkitt lymphoma (2 papers, 2021 to 2024). A rare form of malignant mature B-cell non-Hodgkin lymphoma. "To test the importance of these adaptors, we used pull‐down assays to analyze interactions of endophilin A2‐GFP with the BCR in DG75 Burkitt lymphoma cells in the context of GRB2 or BLNK deletion." (PMID 34323351, 2021).